MUPP (major urinary protein, pseudogene)
Synonyms: MUP
Gene: Transcribed unprocessed pseudogene on chromosome 9 (112,959,134 to 112,962,261, reverse strand). Ensembl gene ENSG00000237906.
Diseases named in the same sentence as MUPP in open-access papers:
MUPP is named in the same sentence as 10 diseases in open-access papers, as found by Europe PMC text mining. Sharing a sentence is not in itself a finding about the gene and the disease.
MUPP shares sentences with these, for which no sentence is quoted: tumor (4 papers); infection (2); Allergy (1); cholestasis (1); hepatic cancer (1); Insulin resistance (1); liver fibrosis (1); Obesity (1); steatosis (1); viral infection (1).